TMED2 (transmembrane p24 trafficking protein 2)
Diseases named in the same sentence as TMED2 in open-access papers (continued):
Sharing a sentence is not in itself a finding about the gene and the disease.
cancer (14 papers, 2017 to 2025). A tumor composed of atypical neoplastic, often pleomorphic cells that invade other tissues. "In this study, we performed a preliminary yet systematic analysis of TMED2 with gene mutations, pathway enrichment, classical immunotherapy biomarkers, drug treatment in pan-cancer." (PMID 40519935, 2025). "We performed GSEA (Gene Set Enrichment Analysis) pathway enrichment analyses and explored the correlations between TMED2 levels and genetic mutation statuses in these cancers." (PMID 40519935, 2025). "Recent research has identified a close association between TMED2 and tumorigenesis, yet its regulatory role and underlying mechanisms in pan-cancer signaling pathways remain unexplored." (PMID 40519935, 2025). "Our results show that the mRNA levels of TMED2 differ significantly between cancerous and normal tissues and are closely associated with cancer prognosis." (PMID 40519935, 2025). "This study provides a comprehensive and in-depth investigation into the association between TMED2 expression and immunotherapy response in various cancers for the first time." (PMID 40519935, 2025). "Using the MuTarget database, we examined the association between TMED2 expression and genetic mutations in a rage of cancer types." (PMID 40519935, 2025). "To further explore the roles played by CAFs, endothelial cells and B cells in HNSC, we used TIMER 2.0 to investigate the association of TMED2/9/10 with various immune infiltrates in human cancers." (PMID 35754792, 2022). "The expression levels of TMED2/9/10 were significantly increased in cancer-associated fibroblasts (CAFs), endothelial cells and B cells." (PMID 35754792, 2022). "TMED2/9/10 were significantly associated with critical clinicopathological features such as age, cancer grade, lymphatic metastasis, and cancer stage." (PMID 35754792, 2022). "Our integrated analysis suggests that targeting TMED2, along with its associated genes and signaling pathways, could represent a new strategy for cancer immune treatment." (PMID 40519935, 2025). "Additionally, analysis of the MuTarget dataset revealed disparities in the expression of TMED2 between mutant and wild-type (WT) groups in various cancers, shedding light on potential mutation mechanisms affecting TMED2 expression during tumorigenesis." (PMID 40519935, 2025). "Second, by constructing the potential regulatory network of TMED2, we revealed its synergistic action in various cancers." (PMID 40519935, 2025). "In summary, TMED2 has promise as an effective target and a biomarker for predicting treatment responses in cancer therapy." (PMID 40519935, 2025). "The top four cancers with a positive correlation between TMED2 levels and ESTIMATE scores were DLBC, LGG, UCS and UVM." (PMID 40519935, 2025). "First, we utilized KEGG (Kyoto Encyclopedia of Genes and Genomes) analysis to investigate the role of TMED2 in tumors and explored its potential molecular mechanisms in cancer." (PMID 40519935, 2025). "Subsequently, we applied four immune infiltration algorithms, including CIBERSORT, MCPCOUNTER, QUANTISEQ and TIMER, to examine the relationship between TMED2 and immune or stromal cells in various cancers." (PMID 40519935, 2025). "Subsequently, we combined the TCGA and GTEx databases for a more comprehensive analysis of TMED2 mRNA expression in pan-cancer." (PMID 40519935, 2025). "On the other hand, after clarifying the expression characteristics of TMED2 in cancer, we focused on exploring its potential as a therapeutic target for immune therapy in various solid cancers within the TIME." (PMID 40519935, 2025). "The top three resistant drugs associated with high TMED2 expression were Zibotentan, GSK429286A, and Temozolomide, according to the GDSC (Genomics of Drug Sensitivity in Cancer) dataset." (PMID 40519935, 2025).
cancer (continued). "We also predicted potential immunotherapy efficacy and drug sensitivity targeting TMED2 in these cancers." (PMID 40519935, 2025). "Given the notable correlations between TMED2 and immune cells, we examined its relationship with different classical immune checkpoints of cancers." (PMID 40519935, 2025). "In ovarian cancer, high TMED2 expression has been connected with increased proliferation and invasion of cancer cells." (PMID 40519935, 2025). "The findings showed a positive relationship between TMED2 expression and the infiltration levels of endothelial cells, neutrophils, dendritic cells, and eosinophils in most cancers." (PMID 40519935, 2025). "Our results demonstrate TMED2’s enormous promise as a therapeutic target, its crucial role in immunity to tumors, and its potential as a prognostic biomarker for several cancer types." (PMID 40519935, 2025). "These analyses collectively indicate that high TMED2 expression is a significant adverse prognostic factor for patient survival, particularly in cancers such as CESC, LGG, MESO, and UVM." (PMID 40519935, 2025). "Using TCGA and GTEX datasets, we observed a striking phenomenon: In comparison to normal samples, TMED2 expression was substantially elevated in almost all cancer cell lines." (PMID 40519935, 2025). "This discovery provides new insights into understanding the biological functions of TMED2 in cancer." (PMID 40519935, 2025). "To further investigate the potential mechanisms underlying TMED2 function, we performed GSEA analysis in various cancers." (PMID 40519935, 2025). "In addition, TMED2 may be crucial in the initiation and advancement of squamous cervical carcinoma because of higher TMED2 expression in this type of cancer and its substantial association with worse overall and recurrence-free survival, according to a multi-omics investigation." (PMID 37928880, 2023). "TIMER2.0, Kaplan-Meier plotter, gene set enrichment analysis (GSEA), Target Gene, and pan-cancer systems were used to predict the potential function of TMED2." (PMID 35135563, 2022). "TMED2, as a critical factor in cell proliferation and differentiation, was found to exhibit cell-type-specific roles in cancer." (PMID 35754792, 2022). "Increased expression of transmembrane p24 trafficking protein 2 (TMED2) is significantly related to the unfavourable outcomes in cancer patients." (PMID 33210454, 2022). "However, previous research has primarily concentrated on TMED2’s function in specific cancer types, leaving its molecular characteristics in pan-cancer contexts underexplored." (PMID 40519935, 2025). "Next, we investigated the prognostic significance of TMED2 across different cancer types." (PMID 40519935, 2025). "We conducted a comprehensive pan-cancer analysis of TMED2 using multiple public databases." (PMID 40519935, 2025). "Notably, among these cancer types, TMED2 expression was highest in tumor cells, underscoring its potential role in tumor biology." (PMID 40519935, 2025). "In the context of cancer, TMED2 may impact tumor growth, metastasis, and its interactions with the immune system." (PMID 40519935, 2025). "On the one hand, we examined TMED2 mRNA expression levels in cancer cell lines and tumor samples." (PMID 40519935, 2025). "TIDE scores, a validated predictive marker of immunotherapy response with high accuracy, were higher in patients with elevated TMED2 expression in most cancers, strongly suggesting that these patients may experience reduced immunotherapy efficacy." (PMID 40519935, 2025). "Therefore, the potential roles and clinical applications of TMED2 in cancer remain to be explored further." (PMID 40519935, 2025). "To explore whether TMED2 functions independently in cancer or collaborates with other genes for co-regulation, we attempted to construct its potential regulatory network." (PMID 40519935, 2025). "Previous research have revealed aberrant expression of TMED2 in specific cancer types." (PMID 40519935, 2025).
cancer (continued). "Additionally, we analyzed the expression of TMED2 across different cancer stages and tumor histology." (PMID 40519935, 2025). "So, we can infer that the transcription factor XBP1 might regulate the expression of TMED2/9/10, disturb their functions, boost immune cell infiltration, thereby promoting abnormal invasion of cancer cells and leading to poor prognosis of HNSC." (PMID 35754792, 2022). "Of note, TMED2, AGR2, and JTB are known to be associated with poor prognosis in other cancers and thus, could be explored as novel biomarkers for predicting chemo-resistance in PDAC." (PMID 32195182, 2020). "TMED2, the sole member of the mammalian β family, displays a cell type-specific role in cancer." (PMID 31878985, 2019). "Further, the expression of TMED2 was related to the cancer grade(P<0.05)." (PMID 29212217, 2017). "Therefore, it is necessary to fully understand the role of TMED2 across different types of cancer." (PMID 39879476, 2025). "TMED2 expression was positively connected with important immune checkpoint markers such as CD274, HAVCR2, PDCD1LG2, and SIGLEC15 in numerous cancer types." (PMID 40519935, 2025). "Across nearly all cancers, the activation of the PI3K/Akt and cell cycle signaling pathways was positively connected with TMED2 expression." (PMID 40519935, 2025). "Correlations between TMED2 expression levels and stromal, immunological, and ESTIMATE scores were assessed using the ESTIMATE algorithm for a variety of cancer types." (PMID 40519935, 2025). "Current studies have found that the expression level of TMED2 in HNSC was up-regulated and related to different cancer stages, races, genders, and ages." (PMID 35754792, 2022). "TMED2 is the sole member of the vertebrate TMED β subfamily and exhibits cell type-specific effects in cancer." (PMID 36524130, 2022). "TMED2 expression was quantified in a series of common cancers via TIMER2.0, and it was found that the level of TMED2 in LUAD tumor tissues was approximately 1.25 log2TPM higher than that in normal tissues (P < 0.05)." (PMID 35135563, 2022). "According to those results, the malignant properties of TMED2 and TMED3 in cancer are cell type-specific." (PMID 33888099, 2021). "Interestingly, we observed that the knockdown of TMED2 had a more pronounced effect on ARF1 than on p-ERK, possibly due to the regulation of ERK via multiple pathways in cancer cells." (PMID 39879476, 2025). "Much like TMED2, the role of TMED3 in cancer is cell type-specific." (PMID 31878985, 2019). "Thus, the removal of TMED2 results in EGFR degradation, reducing cancer cell proliferation." (PMID 40497947, 2025). "In this study, the prognostic and immune-related functions of TMED2 across pan-cancer were comprehensively examined by using public databases, including TCGA (The Cancer Genome Atlas), GTEX (Genotype-Tissue Expression Program), and CCLE (Cancer Cell Line Encyclopedia)." (PMID 40519935, 2025). "However, we also observed that in certain cancers, such as CESC, LUAD, and THCA, many immune checkpoint molecules exhibited a negative correlation with TMED2 expression." (PMID 40519935, 2025).
tumor (14 papers, 2007 to 2025). "We identified pathways like the cell cycle and PI3K/Akt signaling as being significantly associated with TMED2-mediated tumor immunity." (PMID 40519935, 2025). "In our study, TMED2 expression in LUAD tumor tissues was higher than that in normal tissues, and a higher expression of TMED2 isoforms was associated with a worse prognostic outcome in LUAD patients." (PMID 35135563, 2022). "Until routinely applied anticancer drug combinations are available simultaneously targeting HGF, EGF and NFE2L2 mediated pathways, inhibition of overexpressed DYNLL, TNC, NCL and TMED2 may exert anti-tumor effect on HNSCC beyond their diagnostic role." (PMID 32564264, 2020). "While CAV2 and TMED2 exhibited widespread expression in both tumor cells and stromal cells, PLAU demonstrated a relatively specific expression pattern in CAFs and myeloid cells." (PMID 39834857, 2025). "In the high TMED2 expression groups of multiple tumor types, pathways related to cell growth and immunity were significantly enriched." (PMID 40519935, 2025). "The expression of TMED2 in tumor tissues was significantly higher than that in para-tumor tissues (P < 0.05)." (PMID 35135563, 2022). "Therefore, we conjectured those TMED2/9/10 mutations might contribute to tumor development." (PMID 35754792, 2022). "We addressed the importance of TMED2/9/10 in HNSC from the perspectives of its expression in tumor tissues, prognostic value, expression-related genes, GO and KEGG enrichment analysis, single-cell analysis, and immune infiltration analysis, respectively." (PMID 35754792, 2022). "Lentivirus-mediated TMED2 knockdown (using sh-TMED2) was performed to inhibit inflammation and tumor development in LUAD both in vivo and in vitro." (PMID 35135563, 2022). "Furthermore, TMED2’s co-expression in different cell types within the tumor microenvironment was validated through online datasets and single-cell sequencing analysis." (PMID 40519935, 2025). "However, more comprehensive analyses are still lacking, such as protein interaction networks co-expressed with TMED2, single-cell sequencing analyses, and a detailed understanding of its mechanisms in tumor-immune interactions." (PMID 40519935, 2025). "TMED2 demonstrated significant co-expression across tumor cells." (PMID 40519935, 2025). "Recently, it has been shown that TMED2 overexpression was negatively correlated with CD8+ T immune cell levels in HNSC, suggesting that TMED2 might initiate tumor development by altering the levels of immune infiltration in the tumor microenvironment." (PMID 35754792, 2022). "Bioinformatics analysis showed that TMED2 may be associated with LUAD; therefore, we detected the TMED2 expression levels in tumor tissues or LUAD cell lines." (PMID 35135563, 2022). "Therefore, in liver cells, a reduction in TMED2 results in increased liver tumorigenesis and demonstrates a possible tumour suppressor-like property for TMED2." (PMID 31878985, 2019). "Results from single-cell sequencing further demonstrated that tumor cells might express more TMED2." (PMID 40519935, 2025). "Thus, in hepatocytes, a decrease in TMED2 led to an increase in liver tumorigenesis, demonstrating that TMED2 may have tumor suppressor-like properties." (PMID 37928880, 2023). "To further confirm the tumor-inhibition effect of TMED2 and whether it was mediated through the TLR4/NF-κB signaling pathway, we used an activator of TLR4 (sparstolonin B) to boost TLR4 expression and observed the changes in the downstream inflammatory factors using western blotting." (PMID 35135563, 2022). "The results showed that in the clinical staging of CESC and pathological tumor staging of MESO, the expression of TMED2 was higher in stages I and IV compared to stages II and III." (PMID 40519935, 2025). "Genetic ablation of TMED2 was previously shown to induce the degradation of EGFR, therefore resulting in an anti-tumor effect." (PMID 40497947, 2025).
tumor (continued). "In our study, TMED2 knockdown inhibited LUAD development in vitro and in vivo by inhibiting tumor cell proliferation, reducing tumor volume and biomarker levels, and increasing apoptotic levels." (PMID 35135563, 2022). "Thus, depending on cell type, TMED2 may exert either tumour suppressor or oncogenic properties." (PMID 31878985, 2019). "TMED2 has been shown to facilitate EGFR recycling, promoting receptor stability and tumor growth." (PMID 40497947, 2025). "Additionally, TMED2 expression has positive correlation with immunoregulatory pathways, like the cell cycle and PI3K/Akt signaling pathways, which influence tumor growth and expansion." (PMID 40519935, 2025). "Our findings indicated that TMED2 knockdown significantly inhibited the development of LUAD by increasing apoptosis, inhibiting tumor cell proliferation, reducing tumor volume, and decreasing the levels of tumor biomarkers and inflammatory factors by affecting the TLR4/NF-κB signaling pathway." (PMID 35135563, 2022). "Finally, we also detected the levels of tumor biomarker levels in LUAD and found that the expression of TMED2, CEA, NSE, and EGFR in sh-TMED2 mice was reduced (P < 0.05), consistent with the in vitro results." (PMID 35135563, 2022). "In addition, we detected the levels of tumor biomarkers in LUAD and found that the levels of TMED2, CEA, NSE, and EGFR in the sh-TMED2 group were reduced (P < 0.05)." (PMID 35135563, 2022). "TMED2 and TMED3 were respectively reported to be a tumor suppressor and an oncogene in HCC." (PMID 33888099, 2021).
infection (3 papers, 2017 to 2023). The state of being infected such as from the introduction of a foreign agent such as serum, vaccine, antigenic substance or organism. "We found that down-regulation of TMED2 after infection of LV3-1 and LV3-2 suppressed cell proliferation in SKOV3 cells (P < 0.05)." (PMID 29212217, 2017). "The expression of TMED2 was decreased after infection of LV3-1 or LV3-2 in SKOV3 cells." (PMID 29212217, 2017).
TMED2 also shares sentences with these, for which no sentence is quoted: hepatocellular carcinoma (3 papers); multiple myeloma (3); prostate carcinoma (2); Alzheimer disease (1); cervical cancer (1); choriocarcinoma (1); colon cancer (1); kidney disorder (1); mesothelioma (1); ovarian endometrioid adenocarcinoma (1); ovarian mucinous adenocarcinoma (1); ovarian serous adenocarcinoma (1); ovarian serous cystadenocarcinoma (1); squamous cell carcinoma (1).